SMAD3 (SMAD family member 3)
Diseases named in the same sentence as SMAD3 in open-access papers (continued):
Sharing a sentence is not in itself a finding about the gene and the disease.
cancer (continued). "The TGF-β/SMAD3 pathway is so crucial in EMT induction due to its multiple downstream effectors, which are capable of repressing E-cadherin and subsequently enabling upregulation of mesenchymal promoters, then promoting the migration and invasion of cancer cells." (PMID 28611292, 2017). "Finally, for DMRs whose associated genes had increased expression upon treatment with FQI1, we observed enrichment of GO terms for pathways in cancer (e.g. PIAS4, SMAD3, TRAF4, MAP2K1) and RNA transport (e.g. NUP188, EIF3A, NUP35, RAN) in both hyper and hypomethylated DMRs." (PMID 27845898, 2016). "Importantly, we, for the first time, revealed that the protein expressions of ALDH2, CCNE1 and SMAD3 were significant and independent prognostic markers for patients with UTUC, which may facilitate the clinical management of this cancer." (PMID 25408144, 2014). "These seemingly contradictory results might be due, at least in part, to the distinct roles of Smad2, Smad3, and Smad4 in TGF-β signaling in the changing signaling context of cancer progression, resulting in altered target gene expression and ultimately different biological effects." (PMID 16438724, 2006). "We found that SMAD3 expression exhibits negative correlations with many Cancer Hallmark gene-subsets expression compared to KDM7A-DT, which shows positive correlations with genes primarily representing the EMT score and many Cancer Hallmark gene-sets (p< 1.00E-09)." (PMID 38756663, 2024). "Our results suggesting that SARA is an active participant in both SMAD2-inhibitory and SMAD3-stimulatory effects on cancer cell invasion are consistent with the possibility that the targeting of SARA/SMAD binding would be unlikely to provide significant therapeutic benefits for cancer patients." (PMID 35681731, 2022). "In addition, the phosphorylated Smad3 (Ser423/425)), a key factor in TGF-β1 signaling, significantly increased at 8 h after TGF-β1 treatment and disappeared after 48 h, suggesting that the early activation of Smad signaling is essential for TGF-β1-induced EMT in this cancer cell." (PMID 36230768, 2022). "Several immune-related genes exhibited marked variation: for example, CD84 and SMAD3 were abundant in T7 but almost undetectable in T15, whereas KANK1, often relevant in cancer prognosis, was highly expressed in T6 and T15 but absent in T7." (PMID 40764306, 2025). "Several immune-related genes showed pronounced variation: for example, CD84 and SMAD3 were abundant in T7 but nearly undetectable in T15, whereas KANK1, often relevant in cancer prognosis, was highly expressed in T6 and T15 but absent in T7." (PMID 40162205, 2025). "Besides, MS13 treatment in DU 145 and PC-3 cells has shown the downregulation of PPP3CB, TFDP1, SMAD3, and ENDOG, which the anti-cancer activity have not been reported in PCa but noted in other cancers." (PMID 34366863, 2021). "For modules M3, M4, and M5, although the corresponding GO_BP terms were not directly related to cancer, we found PrCa-relevant genes in these three modules, including BTG2, FOS (also known as c-Fos), and CXCR4 in module M3; ARFGAP3 and CDH1 in module M4; and SMAD3 and MXI1 in module M5." (PMID 25418933, 2014). "Consequently, EGFR was lowly expressed in the cancer group versus the normal group in LUAD without a statistical difference (P-value: 0.19) and this expression pattern was similar to ESR1 (P-value: 0.42), MYC (P-value: 0.067), RELA (P-value: 0.058) and SMAD3 (P-value: 0.13)." (PMID 33506873, 2021).
infection (49 papers, 2007 to 2025). The state of being infected such as from the introduction of a foreign agent such as serum, vaccine, antigenic substance or organism. "The data presented here indicate that HCMV encodes multiple mechanisms to reduce SMAD3 expression and block canonical TGFβ signaling suggesting an anti-viral role for TGFβ during lytic infection." (PMID 34411201, 2021). "Infection of CD34+ HPCs with miR-UL22A-deficient virus also resulted in a lower frequency of reactivation relative to wild type virus, while infection with miR-UL22A-deficient/SMAD3 shRNA virus restored reactivation potential." (PMID 34299120, 2021). "Infection with a miR-UL22A-deficient HCMV virus resulted in increased SMAD3 expression in NHDF cells and restored SERPINE transcript levels in HPCs, indicating that miR-UL22A impedes TGF-β signaling." (PMID 34299120, 2021). "Therefore, we also performed outgrowth experiments with MDA-231 cells following infection with adenovirus encoding either EGFP (Ad-GFP)- or SMAD3 (Ad-Smad3)." (PMID 30318519, 2018). "Our results revealed a significant increase in Smad3 phosphorylation levels on day 14 post-infection." (PMID 41011177, 2025). "For validation of our Ad-delivery approach, Western analysis on Ad-infected ASM cell lysates 24 h post-infection confirms robust Smad3 expression in the Smad3 OE cells, and robust Smad3 expression in the Smad3 OE cells, normalized to total cellular protein." (PMID 37693008, 2023). "Some upstream regulators were common between both parasite stages (MYC, KLF4, and SMAD3) albeit with variations in the number and/or identity of downstream targets in each type of infection." (PMID 35430587, 2022). "We next evaluated the effects of decreased Smad2 and/or Smad3 expression at day 7 after lentiviral shRNA vector infection." (PMID 34691193, 2021). "We have previously determined that expression of a SMAD3 shRNA in place of miR-UL22A results in SMAD3 protein levels similar to WT infection." (PMID 34411201, 2021). "In diabetic models, Smad3 homozygous or heterozygous KO induce AS in genes participate in immune and infection pathways." (PMID 33369170, 2021). "To investigate the contribution of miR-UL22A targeting of SMAD3 to the block in canonical TGFβ signaling observed during HCMV lytic infection, we assessed SMAD3 transcript levels after infection with WT and ΔmiR-UL22A virus." (PMID 34411201, 2021). "The functional significance of SMAD3 targeting by miR-UL22A during lytic infection is underscored by the increased IFNα and IFNβ expression and secretion upon infection with a ΔmiR-UL22A mutant virus." (PMID 34411201, 2021). "The Kinexus microarray did not contain antibodies against the activated form of several transcription factors (including SREBF1-2, CREBBP and SMAD3) that our TFactS analysis of transcriptomics data identified as modulated by infection." (PMID 28480889, 2017). "Simultaneous infection of C3H10 T1/2 with SMAD3- and VDR-expressing lentivirus led to an elevation in RANKL expression." (PMID 28216630, 2017). "In order to dynamically monitor TGFβ signaling activities during embryonic stem cell (ESCs) maintenance and differentiation, we expressed GFP-tagged Smad2 and Smad3 in human ESCs through lentiviral infection." (PMID 26905010, 2016). "The Smad3 protein in the liver of C. sinensis-infected mice was increased dramatically as the infection developed, which was consistent with the mRNA expression of Smad3." (PMID 25649869, 2015). "Both Smad2 and Smad3 are significantly phosphorylated in the ceca from Salmonella-infected chickens at 4 days post-infection." (PMID 26664962, 2015). "Protein expression of TGF-β1, TGF-β2, SMAD3, and phospho-SMAD3 were analyzed by indirect immunofluorescence at 0 h, 12 h, and 24 h post-infection (p.i.)in HCE cells." (PMID 18776948, 2008).
infection (continued). "Levels of mRNA for TGF-β isoforms 1, 2, and 3 as well as for SMAD2 and SMAD3 were measured by reverse transcription polymerase chain reaction (RT–PCR) at 0 h, 4 h, 8 h, 12 h, and 24 h after infection." (PMID 18776948, 2008). "Moreover, infection of LPCs with Ad-3SA promoted TGF-β-induced linker phosphorylation of Smad3, and infection of LPCs with Ad-EPSMs increased the C-terminal phosphorylation of Smad3, as indicated by stimulation with TGF-β." (PMID 38604156, 2024). "The expression levels of Tgfb1, Smad3, type IV collagen gene, and type VI collagen gene in diaphragms were evaluated at protein and mRNA levels using Western blot and q-PCR at different days post-infection." (PMID 37834451, 2023). "The results showed that the infection efficiency of pLVX-TetOne-SMAD3 lentivirus was close to 60%, while the infection efficiency of pSicoR-Ef1a-mCherry-shRNA1/2/3-SMAD3 lentivirus virus could reach 80%–90%." (PMID 36313568, 2022). "Alpha-smooth muscle actin (α-SMA), collagen I, collagen III, TGF-β1, Smad2, Smad3, and Smad4 showed a significant increase in mitochondrial RNA (mRNA) and protein expression compared with the control group at 7 and 9 weeks post-infection (wpi), while an opposite effect on Smad7 was observed." (PMID 36474240, 2022). "In the ileal network, JAK2 and CREB1, as well as SMAD2, SMAD3 and ERK2 (MAPK1) seem to play a central role in the intracellular PPI signalling driven by viral miRNAs and viral proteins, respectively, and JAK2 and both SMAD2 and SMAD3 were also upregulated upon infection." (PMID 35501398, 2022). "We observed a significant decrease in SMAD3 transcript levels upon infection with WT HCMV at 3 (p = 0.05) and 6 (p<0.01) days post-infection (dpi), suggesting that the decrease in total and phosphorylated protein is due, at least in part, to a decrease in transcription of SMAD3." (PMID 34411201, 2021). "Moreover, we observed only a partial restoration in SMAD3 transcript levels after ΔmiR-UL22A infection, although significantly increased (p = 0.02) compared to WT-infected cells at 6 dpi." (PMID 34411201, 2021). "By qPCR analysis of whole‐kidney RNA, Smad2 expression in TC‐treated mice was statistically equivalent to that in vehicle‐treated mice across the course of infection, while Smad3 expression was significantly suppressed in TC‐treated mice at 7 dpi, recovering by 28 dpi." (PMID 32227630, 2020). "P.g.-infection induced activation of Smad2, Smad3, and ERK1/2." (PMID 32139740, 2020). "The average % reduction of MDA-231 outgrowth upon Ad-SMAD3 infection (~20%), although statistically significant from Ad-GFP transduced group, was even slightly lower than what we saw in our plasmid transfection setting (possible reason for this is discussed later)." (PMID 30318519, 2018). "However, after infection of AdSmad3, these markers were significantly upregulated by mechanical stretch, indicating that inhibition of Smad3 is the key mechanism mediating the HSF1-induced anti-fibrotic effect." (PMID 28091697, 2017). "Transfection of these cells with a Smad3 expression vector caused induction of p21WAF1/CIP1 expression while, conversely, knock-down of Smad3 by infection with shRNA retroviruses (pRS-Smad3 n°1 and n°2) showed that induction of p21WAF1/CIP1 by activated Notch1 is Smad3-dependent." (PMID 27384993, 2016). "Interestingly, concomitant Ad-Smad3/Ad-FoxO3 infection significantly reversed cytoplasmic phosphorylated Smad3, largely (p = 0.05) reduced nuclear phosphorylated Smad3, and significantly reduced nuclear total Smad3 compared to Ad-Smad3 infection alone." (PMID 37693008, 2023). "Researchers have identified increases in the expression of several genes (SMAD3, SMAD4, COL1A1) related to TGF-β and associated with evidence of fibrosis-associated cell types, including fibroblast and stellate cell lines, in acute stages of infection in sheep." (PMID 29970179, 2018).
infection (continued). "Interestingly, Ha-Ras-expressing cells also exhibited high protein levels of non-phosphorylated Smad3 at 6 h and 24 h post-infection, which were not, however, associated with increased levels of transcripts coding for Smad3." (PMID 21362163, 2011). "TGF-β1 expression was significantly upregulated following SARS-CoV-2 wild-type infection, consistent with previous reports linking SARS-CoV-2 to TGF-β/Smad3 signaling activation and apoptosis induction in multiple organs." (PMID 40879372, 2025). "We then carried out cell proliferation analyses, and the results showed that infection with Ad-Smad3 in LPCs augmented TGF-β-induced cytostasis, and infection with Ad-EPSMs markedly enhanced the cytostatic effect of TGF-β." (PMID 38604156, 2024). "Diaphragms were obtained post-infection, and the expression levels of the TGF-β1/Smad3 pathway-related genes and collagen genes (type IV and VI) were observed during the process of collagen capsule formation." (PMID 37834451, 2023). "Critically, replacing the miR-UL22A hairpin locus with an shRNA targeting SMAD3 reduces type I IFN expression and secretion, along with ISG induction, to levels seen during WT infection." (PMID 34411201, 2021). "Kidneys of TC‐treated mice exhibited a higher Smad2:Smad3 ratio than vehicle‐treated mice, beginning before the onset of UTI and continuing throughout the course of infection." (PMID 32227630, 2020). "In primary infection, the SMAD protein Smad2 was found to interact with Acvr1b; whereas in secondary infection, Smad2, Smad3, and Smad7 were found to interacted with Acvr1b." (PMID 25341656, 2014). "The R-SMADs Smad2 and Smad3, which, upon phosphorylation, interact with Co-SMAD and translocate to the nucleus, were identified as key proteins in primary and secondary infection." (PMID 25341656, 2014). "Examination of the ontologies enriched in this set of up-regulated genes showed genes known to play a role in infection processes, including NR3C1, PTPRC, SFRS1, SFRS5, SMAD3, C3 and DDX58." (PMID 22363497, 2012). "Interestingly, we obtained the enrichment of TFs known to be involved in immune regulation, such as SMAD3, and IRF and STAT family members, all shown to have a role during infection by viral and bacterial pathogens." (PMID 38956024, 2024). "Following establishment of the efficiencies of our Ad-infections and validation of increased transcriptional activities following OE of Smad3 and FoxO3, Western blotting for Smad3 and FoxO3 was performed on Ad-infected whole ASM cell lysates 24 h post-infection." (PMID 37693008, 2023). "In the current study, using GFP fluorescent intensity measurements (for Ad-GFP, Ad-FoxO3, and Ad-Smad3/Ad-FoxO3 cells, all containing IRES elements that precede the GFP coding sequence), we determined Ad-infection efficiencies between 55% and 65% between 24 and 72 h (data not shown)." (PMID 37693008, 2023). "We found promising master regulators of duck genes in lung and ileum (RUNX2, SMAD3, SMAD4, and ETS1), which could be responsible for the duck’s effective differential gene expression in response to HPAI infection." (PMID 35205087, 2022). "Indeed, after AdSmad3 infection and TGF-β treatment, over 90% of GFP-expressing SMCs were Smad3-overexpressing cells." (PMID 24718260, 2014). "In addition, infection of LPCs with Ad-3SA or Ad-EPSM caused a reduction in the C-terminus and linker phosphorylation of Smad3, respectively, in the presence or absence of TGF-β." (PMID 38604156, 2024). "The hypothesis that SMAD3 and IRF7 work together in the initial induction of IFNβ is supported by the observations using ΔIFNAR cells, which are capable of the initial IFNβ production following infection but cannot amplify the response." (PMID 34411201, 2021). "Infection with Ad-control did not modulate the Smad3 expression and phosphorylation." (PMID 22384127, 2012).
infection (continued). "Transcriptome arrays showed no significant changes of TGF-β receptors 1 and 2 and Smad-3 expression, whereas a strong expression of BAMBI with upregulation after in vitro infection of COPD lung tissue was demonstrated." (PMID 20513241, 2010). "To determine which signaling pathways influence the release of growth factors in murine BMSCs, we evaluated p-TGFβ receptor 1 (p-TGFβR1), p-Smad3, p-PI3K, p-Akt, and control actin protein levels in murine BMSCs treated with vehicle or JTE013 with or without 8 h Aa infection." (PMID 36834810, 2023). "We observed a reduction in p-Smad3 in murine BMSCs treated with JTE013 or the S1PR2 shRNA and infected with Aa compared to JTE013 or the S1PR2 shRNA-treated BMSCs without Aa infection." (PMID 36834810, 2023).